NRG1 (neuregulin 1)
Diseases named in the same sentence as NRG1 in open-access papers (continued):
Sharing a sentence is not in itself a finding about the gene and the disease.
breast carcinoma (continued). "However, little is known about the factors involved in Nrg1 enhancer activation, and how they regulate Nrg1 overexpression in breast cancer cells in patients with diabetes." (PMID 36707514, 2023). "Furthermore, CAFs that express specific proteins are also involved in tumor resistance to targeted therapy, such as CAFs expressing high-level Neuregulin 1 (NRG1) can lead to trastuzumab resistance in HER-2+ breast cancer through the HER3/AKT pathway." (PMID 37666813, 2023). "NRG1 levels were positively correlated with NOTCH activity in breast cancer patients." (PMID 36707514, 2023). "We examined whether the Notch signaling pathway is involved in Nrg1 upregulation in breast cancer cells under hyperglycemic conditions." (PMID 36707514, 2023). "Specific to breast cancer cells, high carbohydrate levels enhance expression of the neuregulin 1-gene, an endogenous ligand for the HER3 receptor, as well as multiple glucose-metabolism-related long-coding ribonucleic acids (lncRNAs) that increased risk of breast cancer progression." (PMID 37626871, 2023). "The NRG1/HER3 axis confers resistance to trastuzumab in HER2-positive breast cancer cells." (PMID 36707514, 2023). "NRG1 gene fusion takes part in the progression of breast cancer and lung adenocarcinoma." (PMID 35321516, 2022). "Furthermore, the analysis of the ERBB3 ligand NRG1 unveiled very low levels in breast cancer tissue compared to normal specimens, with minimal differences among clinical and molecular breast cancer subtypes." (PMID 35406375, 2022). "Collectively, our data in HER2+ breast cancer cells highlight that NRG1 may exert both pro- and anti-proliferative effects, and may reduce the efficacy of anti-HER2 agents, whereas NRG4 may boost the anti-proliferative effects of anti-ERBB2 agents." (PMID 35664762, 2022). "In addition, a previous study showed the downregulated NRG1 expressions in breast cancer cell lines compared to normal ones." (PMID 35443634, 2022). "In addition, we found that high expression of PRCP correlates with increased expression of IGF1/NRG1 and their target genes and earlier recurrence of endocrine treated ER+ breast cancer patients." (PMID 36332175, 2022). "Our data suggested that the treatment of HER2+ breast cancer cells with NRG1 may sustain or restrain cell proliferation, as well as reduce the efficacy of ERBB2 targeting agents." (PMID 35664762, 2022). "Intriguingly, higher ERBB3 expression levels correlate with lower relapse-free survival in basal-like/triple-negative (HER2-/ER-/PR-) breast cancer patients, and NRG1/ERBB3/ERBB2 axis was shown to promote anchorage-independent cell growth in basal-like/triple-negative breast cancer cells." (PMID 35664762, 2022). "Our observation of a positive correlation between ERBB4 mRNA levels and increased relapse-free patients’ survival in the luminal A subtype is in line with a previous study showing that the activation of ERBB4 signaling by NRG1 restrains the growth of breast cancer luminal cells." (PMID 35664762, 2022). "We also report a search for NRG1 fusions and rearrangements in nearly 600 breast cancers." (PMID 33413557, 2021). "Secondly, we confirm that around 0.5% of breast cancers have NRG1 fusions of this activating type, but many more cases have rearrangements of the NRG1 gene that seem more likely to inactivate the gene or, as in MDA-MB-175, are too complex to interpret from DNA sequence alone." (PMID 33413557, 2021). "On the other hand, the NRG1 gene is frequently silenced by methylation in breast cancers and NRG1 may be the principal tumor suppressor gene that leads to loss of the short arm of chromosome 8 in many breast and other epithelial cancers." (PMID 34044811, 2021). "Activation of HER4 by NRG-1 thus delays mitosis and reduces breast cancer cell proliferation." (PMID 34885957, 2021).
breast carcinoma (continued). "Ultimately, this tailored combination therapy represents a novel treatment approach from which not only luminal breast cancer patients but possibly other tumor entities with high levels of stromal NRG1 could benefit." (PMID 33692466, 2021). "Although some studies have proposed that NRG1 may promote tumor growth, NRG1 could also act as a tumor suppressor in breast cancer." (PMID 33591377, 2021). "Thus, we next explored NRG1 expression in a collection of breast cancer datasets generated by laser capture microdissection (LCM) of the stromal and epithelial compartments (GSE10797;, GSE14548;, GSE35019 and GSE83591)." (PMID 33692466, 2021). "This patient had a history of breast cancer treated with neoadjuvant chemotherapy, radiation and surgery, so there are many factors that could potentially lead to NRG1 rearrangements." (PMID 34680187, 2021). "However, additional studies are necessary to determine if KLF4 also directly regulates NRG1 expression in breast cancer." (PMID 32552913, 2020). "After establishing that ErbB3 signaling on macrophages was important for enhancing breast cancer cell migration across the endothelial cell layer, we then tested whether altering expression of the ErbB3 ligand NRG1 by the cancer cells was important." (PMID 29636067, 2018). "Neuregulin 1, which is encoded by the NRG1 gene and acts on the ERBB family of tyrosine kinase receptors, could behave as a tumour suppressor in breast cancer cells." (PMID 28703219, 2017). "Phase 2 clinical data published with anti-ErbB3 mAbs evaluated in lung, ovarian, and breast cancer have suggested that NRG1 expression levels may be a potential biomarker to enrich for patients who will respond to therapy." (PMID 28723928, 2017). "Exogenous NRG1 partially rescued breast cancer cells from growth inhibition by lapatinib." (PMID 25691057, 2015). "NRG1 has been implicated in lapatinib resistance as well as overcoming the inhibitory effect of gefitinib and trastuzumab treatment in HER2-overexpressing breast cancer cells." (PMID 25691057, 2015). "HER1-4 and NRG1 levels in normal and breast cancer tissue among postmenopausal patients." (PMID 23991224, 2013). "On the other hand, NRG1 has been shown to be silenced by methylation in breast cancers, in which case tumour cells may be deprived of an important growth factor." (PMID 23991224, 2013). "NRG1 is up-regulated in several types of cancer including breast cancer, lung cancer, pancreatic cancer, and over-expression of NRG1 may activate downstream signaling pathways such as ERBB3/ERBB2 pathway, leading to the stimulation on cancer cell proliferation, invasion, and drug resistance." (PMID 40959099, 2025). "Additionally, NRG1 has been shown to promote the progression in breast cancer." (PMID 37205121, 2023). "Furthermore, a modest increase in NRG1 mRNA levels was observed in the basal-B subgroup, while the stratification for clinical breast cancer subtypes highlighted a high variability in the triple-negative subgroup without significant differences with the other subtypes." (PMID 35406375, 2022). "Thus, we suggest that the utility of NRG1 as a predictive biomarker to anti-HER3 therapies in luminal breast cancer may be provided by the stromal compartment, while analysis of bulk tumour tissues may dilute its detection." (PMID 33692466, 2021). "Other NRG1-positive tumor types include pancreatic, gallbladder cancer, renal cell carcinoma, bladder cancer, ovarian cancer, breast cancer, neuroendocrine tumor, sarcoma and CRC, showing how an actionable medication could benefit a large group of patients with a large variety of tumors." (PMID 34680187, 2021). "In addition, NRG1 was identified as one of 15 breast cancer anti-estrogen resistance genes." (PMID 29682206, 2018).
breast carcinoma (continued). "Furthermore, transmembrane Nrg1 expressed in MCF7 cells activated HER receptors and caused the cells to be sensitized to trastuzumab, a monoclonal antibody that binds HER2 and is used to treat HER2-positive breast cancer." (PMID 29230082, 2017). "As we have shown that the NRG1/HER3 pathway was one of the mechanisms of acquired lapatinib resistance in HER2-overexpressing breast cancer cell lines, this pathway might also have a potential role in breast cancer cells that have innate resistance to lapatinib." (PMID 25691057, 2015). "We next investigated the effect of antibody treatment on NRG1-induced HER2/HER3 heterodimerization and downstream signaling across the three breast cancer cell lines." (PMID 41538393, 2026). "For breast carcinomas, it was shown that neuregulin 1 (ligand for ERBB3 and ERBB4 tyrosine kinase receptors), but not Wnt3A, is indispensable for the isolation and long-term culture and expansion of breast cancer PDOs." (PMID 40863456, 2025). "Most lung cancer and colorectal cancer patients with NRG1 fusions harbored FDA-approved or potential drug targets, whereas those diagnosed with breast cancer harbored fewer such targets." (PMID 40730881, 2025). "NRG1 belongs to the epidermal growth factor (EGF) family, which is crucial in linking hyperglycemic memory in breast cancer cells to malignant tumor progression." (PMID 39727977, 2024). "NOTCH activity is correlated with NRG1 levels, and high NRG1 levels predicts poor outcomes, particularly in HER2-positive breast cancer patients." (PMID 36707514, 2023). "Zenocutuzumab was evaluated in patients with NRG1 fusion-positive solid tumors, including NSCLC, breast cancer, and pancreatic cancer." (PMID 37947595, 2023). "Using univariate Cox regression analysis, a total of 4 autophagy-related genes (EIF4EBP1, IFNG, NRG1, TP63) were significantly correlated with overall survival (OS) of breast cancer." (PMID 35480110, 2022). "Third, ligand-mediated activation of ERBB3 has been shown to result in PI3K/AKT-mediated resistance to TKIs in a variety of cancers, including ERBB2-amplified breast cancer cells stimulated with ERBB3 ligands, NRG1 or HRG." (PMID 34675407, 2022). "Schwarz and colleagues found that induction of neuregulin-1 and autocrine activation of HER3-PI3K mediates acquired resistance to T-DM1 in HER2+ breast cancer xenografts." (PMID 35158800, 2022). "Of note, NRG1 is a well-known activator of ERBB3/ERBB2 dimers, which are known to play a role in the context of HER2+ breast cancer aggressiveness." (PMID 35664762, 2022). "Despite all different cultures of CAFs were derived from luminal breast cancer tissue, they showed variable capacities to activate the HER3 pathway in luminal breast cancer cells via NRG1." (PMID 33692466, 2021). "We analysed genomic rearrangements and transcripts of NRG1 in MDA-MB-175 and a panel of 571 breast cancers." (PMID 33413557, 2021). "Taken together, these results indicate that CAFs isolated from tumour tissue of luminal breast cancer specimens differently activate the HER3 pathway and regulate proliferation and/or migration of cancer cells via NRG1 secretion." (PMID 33692466, 2021). "Next, we analysed mRNA transcript and protein expression levels of NRG1 in the CAF lines and in the two luminal breast cancer cell lines." (PMID 33692466, 2021). "The NRG1 fusion of the breast cancer cell line MDA-MB-175 was the first NRG1 fusion reported and serves as a model of such fusions and the proposed autocrine loop." (PMID 33413557, 2021). "While this gene set was based on experiments conducted on a breast cancer cell line (MCF-7) and caution should be exercised in interpreting implications in brain, NRG1 is generally involved in activation of proliferation, survival, and differentiation." (PMID 32228684, 2020). "In breast cancer, EGFR silencing decreased NRG1 expression and invasion, while NRG1 silencing decreased EGFR expression and proliferation." (PMID 32552913, 2020).
breast carcinoma (continued). "We observed that, upon stimulation with NRG-1, MCF7 breast cancer cells displayed a robust increase of LINC00052 RNA levels along with increased HER3 phosphorylation." (PMID 28036286, 2017). "To do so, we analysed HER-1–4 and ligand NRG1 mRNA expression pattern in breast cancer and normal breast tissue and correlated findings to ER mRNA expression (ESR1) and plasma, normal tissue and breast cancer tissue estrogen levels previously determined." (PMID 23991224, 2013). "While Neuregulin-1 (NRG1) and EGF growth factors induce an increase of hMena expression, Herceptin treatment down-regulates hMena in breast cancer cell lines overexpressing HER2." (PMID 21209853, 2010). "This study revealed that NRG-1 activates MMP-9 via multiple signaling pathways (ERK-, PKC-, and p38 kinase-pathway) in human breast cancer cell lines." (PMID 16901352, 2006). "Given that DAPT-induced Notch inactivation attenuated hyperglycemia-induced Nrg1 overexpression, we hypothesized that the dual inhibition of NOTCH and HER2 could effectively reduce tumor burden, especially in breast cancer patients with hyperglycemia." (PMID 36707514, 2023). "Studies have shown that the neuregulin 1 (NRG1) and human epidermal growth factor (EGF) receptor (HER) signaling pathway promotes carcinogenesis and the pathogenesis of multiple human cancers, including breast cancer (BC)." (PMID 37389721, 2023). "In in vitro experiments, pertuzumab failed to suppress HER2-HER3 dimers in HER2+ breast cancer cells provided with a saturating concentration of neuregulin-1." (PMID 35158800, 2022). "In this study, we investigated the potential role of NRG1/ERBB3/ERBB2 signaling in different clinical and molecular subtypes of breast cancers, by combining metanalysis on patients’ survival and gene expression, and by exploring in vitro potential effects induced by the activation of this pathway." (PMID 35406375, 2022). "We searched for NRG1 rearrangements in 571 breast cancers subjected to genome sequencing and transcriptome sequencing and found four cases (0.7%) with fusions, WRN-NRG1, FAM91A1-NRG1, ARHGEF39-NRG1, and ZNF704-NRG1, all splicing into NRG1 at the same exon as in MDA-MB-175." (PMID 33413557, 2021). "Our results highlight the complexity of rearrangements of NRG1 in breast cancers and confirm that some do not activate but inactivate." (PMID 33413557, 2021). "Many of the rearrangements of NRG1 that we found in breast cancers did not or were unlikely to create an activating fusion, including the two fusions that were out of frame." (PMID 33413557, 2021). "This suggests that an autocrine signaling is unlikely in breast cancer and rather the activation of HER3 in luminal cancer cells might be dependent on NRG1 expressed by cells in the tumour microenvironment." (PMID 33692466, 2021). "These authors point out that the mechanisms of resistance to NRG1-targeting agents could be potentially explained by the upregulation of NRG1 as well as parallel pathway activation, as seen in HER2-positive breast cancer models and ALK-positive lung cancer." (PMID 34680187, 2021). "Probably our and others’ estimates of around 5% of breast cancers having breaks within NRG1 by FISH includes many cases where there is no fusion." (PMID 33413557, 2021). "Interestingly, HER4 mRNA expression has been found to correlate with BRCA1 mRNA expression in human breast cancer samples and requires BRCA1 activity for NRG-1-mediated breast cell growth inhibition, as shown by in vitro and in vivo BRCA1 knockdown studies." (PMID 34885957, 2021). "Collectively, these results demonstrate that NRG1 is expressed by CAFs in the stroma of luminal breast cancer patients and reinforce the concept of a paracrine-driven activation of HER3 in the luminal breast cancer subtype." (PMID 33692466, 2021). "In contrast, recombinant NRG1 was able to activate HER3 in MCF7 breast cancer cells (data not shown)." (PMID 33327495, 2020).
breast carcinoma (continued). "Silencing the expression of P-Rex1 from breast cancer cells largely impairs the elevation in Rac-GTP levels in response to growth factors such as EGF (ErbB1/EGFR ligand) and heregulin/neuregulin-1 (HRG, ErbB3/ErbB4 ligand), drastically affecting the motile capacity of these cells." (PMID 27351228, 2016). "In addition, both parental and lapatinib-resistant breast cancer cells were sensitive to SGP1, which inhibits binding of NRG1 and other HER3 ligands." (PMID 25691057, 2015). "We did not observe any significant difference in NRG1 mRNA levels between breast cancer and normal tissue; thus, further studies are required to understand NRG1s role or function in endocrine breast cancer and treatment." (PMID 23991224, 2013). "Altogether, our data highlight that NRG1 may exert both pro- and anti-proliferative effects on HER2+ breast cancer cellular models, and may reduce the efficacy of anti-HER2 agents, whereas NRG4 consistently boosts the anti-proliferative effects of anti-HER2 agents." (PMID 35664762, 2022). "This is not surprising because NRG1 can be pro-apoptotic and is inactivated in some breast cancers." (PMID 33413557, 2021). "NRG1 protein expression was evaluated in the three different cell types: western blot analysis of cell lysates showed strong NRG1 protein expression in the MDA-MB 231 cells, and a second breast cancer triple negative cell line BT549, showed less expression in the HUVECs and macrophages." (PMID 29636067, 2018). "Our study demonstrated that the NRG1 protein expression levels increased in response to lapatinib treatment in HER2-overexpressing breast cancer cell lines, and lapatinib could not sustain its inhibition of HER receptor signalling." (PMID 25691057, 2015). "However, our results demonstrated that HER2Mab not only did not inhibit MCF7 cell proliferation, but it promoted proliferation of the low HER2 expressing MCF7 breast cancer cells in the absence of HER3 ligand NRG1." (PMID 23342251, 2012). "Although the diabetic status of breast cancer patients was unknown, we demonstrated that patients with high NOTCH activity had upregulated NRG1 expression, regardless of breast cancer subtype, and had more accessible chromatin structure within the NRG1 enhancer region." (PMID 36707514, 2023). "It is interesting to postulate that an ADAM17 inhibitor may be beneficial for breast cancer patients who are not responding to trastuzumab who also express low levels of HER2 because it would increase membrane-bound Nrg1 and prevent it from binding and activating HER3." (PMID 29230082, 2017). "Although NRG1 was expressed only from HP1, and was focally amplified in the genome, it was not overexpressed relative to other breast cancer samples within the cohort." (PMID 39406235, 2024).